LCN2 (lipocalin 2)
Diseases named in the same sentence as LCN2 in open-access papers (continued):
Sharing a sentence is not in itself a finding about the gene and the disease.
hemochromatosis (2 papers, 2020 to 2022). A disorder of iron metabolism characterized by a triad of HEMOSIDEROSIS; LIVER CIRRHOSIS; and DIABETES MELLITUS. "As extracellular LCN2 is strongly expressed upon infection with Salmonella, LCN2 expression is associated with reduced macrophage total iron content, which is based on previous observations in hemochromatosis mice." (PMID 35743233, 2022).
Hyperinsulinemia (2 papers, 2019). An increased concentration of insulin in the blood. "As HFD-fed and STZ-injected mice are characterized by hyperinsulinemia and insulinopenic state, respectively, it is important to understand whether the presence or absence of insulin affects the expression of LCN2." (PMID 30761088, 2019).
infertile (2 papers, 2024 to 2025). "Interestingly, the authors also observed augmented LCN-2 mRNA and protein levels in the testes of two different infertile mouse models (induction of cryptorchidism and busulfan-led induction of apoptosis in germ cells)." (PMID 38396890, 2024).
invasive carcinoma (2 papers, 2009 to 2024). A carcinoma that is not confined to the epithelium, and has spread to the surrounding stroma. "Other differentially expressed transcripts include S100A7, LCN2, CXCL14, and CD207 (decreasing expression from premalignant lesions to invasive carcinoma), as well as IDO1, IL6, IL8, THBS1, and FN1 (increasing expression from premalignant lesions to invasive carcinoma)." (PMID 38706595, 2024).
iron overload (2 papers, 2009 to 2023). "We used siRNA and plasmid to knockdown or overexpress Lcn2, respectively, which partially offset or replicated the therapeutic effect of sh-Repin1 in iron-overload-induced osteogenesis dysfunction." (PMID 37749079, 2023). "Both Lcn2 and HFE2 are associated with iron regulation, and mutation in the HFE2 gene is causative for hematochormasis, which is characterized by iron overload." (PMID 20145715, 2009).
joint disease (2 papers, 2020 to 2022). "In sharp contrast, beta-defensin 2 levels (> 1.88 ng/mL) and lipocalin 2 (> 24.7 ng/mL) were elevated in the majority of patients with monomorphic skin (93% and 73%, respectively) and entheseal (both 53%), but not joint disease (27% and 20%, respectively)." (PMID 32051028, 2020). "In sharp contrast, beta-defensin 2 and lipocalin-2 levels were elevated in the majority of patients with monomorphic skin (93% and 73%) and entheseal (both 53%), but not joint disease (27% and 20%)." (PMID 32051028, 2020).
lung squamous cell carcinoma (2 papers, 2017). "From TGCA database and immunohistochemistry analysis, HK2 and LCN2 expression increased in lung squamous cell carcinoma and their related adjacent normal tissues." (PMID 29285270, 2017). "Both HK2 and LCN2 expressions significantly increased in cancer tissues when compared with normal tissues in lung squamous cell carcinoma." (PMID 29285270, 2017).
meningioma (2 papers, 2019 to 2020). A generally slow growing tumor attached to the dura mater. "Proteins involved in neutrophil degranulation, such as ARSA, GCA, FUCA1, PRTN3, ELANE, MNDA, and LCN2, were identified uniquely or with differential abundance in male meningiomas." (PMID 32587372, 2020).
metastasis (2 papers, 2023 to 2025). The spread or migration of cancer cells from one part of the body (where they first appeared) to another. "LCN2 was significantly higher in the osteolytic bone metastasis group than in the local and osteoblastic bone metastasis groups." (PMID 37408474, 2023).
migraine (2 papers, 2024 to 2025). "Compared with the control group, the serum LCN2 level in patients with migraine was significantly higher, and a positive correlation was observed between the visual analog scale score, the number of days with pain, and the LCN2 level." (PMID 37450927, 2024). "The shared pathways, such as those regulated by Il1b, Nox1, and Lcn2, are involved in both ferroptosis and immune responses, suggesting that targeting these pathways could modulate multiple aspects of the comorbid migraine and TMDs." (PMID 41465107, 2025). "Therefore, LCN2R is expressed in microglia, indicating that astrocyte-derived LCN2 may act on microglia, stimulate crosstalk, and regulate migraines and other CNS neuroinflammatory diseases." (PMID 37450927, 2024).
morbid obesity (2 papers, 2022 to 2024). An excess of body weight, normally defined as an individual with a body mass index greater than 35 or a body weight greater than one hundred percent of ideal body weight. "This suggests that LCN2 and irisin might be sensitive markers of the metabolic milieu for subjects with morbid obesity during such exercise training forms." (PMID 39683642, 2024). "The primary aim of this study is to explore the relationship between Lcn2 inflammatory biomarkers and the TE status of subjects with morbid obesity who are undergoing laparoscopic sleeve gastrectomy (LSG); the secondary aim is to evaluate the Zn-to-Cu ratio in those with a detected TE deficiency." (PMID 35722455, 2022).
Mycobacterial Infections (2 papers, 2012 to 2019). "Importantly, despite a common role for Lcn2 in regulating chemokines during mycobacterial pulmonary infections, Lcn2 deficient mice are more susceptible to acute M.bovis BCG, but not low dose M.tuberculosis pulmonary infection." (PMID 23185529, 2012). "Importantly, despite a common role for Lcn2 in regulating CXCL9 expression during mycobacterial pulmonary infections, Lcn2KO mice are more susceptible to acute M.bovis BCG pulmonary infection, but not low dose M.tuberculosis pulmonary infection." (PMID 23185529, 2012). "Macrophage Lcn-2 has previously been shown to reduce granulomatous inflammation in mycobacterial pulmonary infections." (PMID 30845693, 2019). "In this study, we reveal a new role for Lcn2 in regulating lung inflammation and T cell accumulation during mycobacterial pulmonary infections, by restraining CXCL9 induction." (PMID 23185529, 2012). "In the present study, using models of acute and chronic mycobacterial pulmonary infections, we reveal a novel role for Lcn2 in constraining T cell lymphocytic accumulation and inflammation by inhibiting inflammatory chemokines, such as CXCL9." (PMID 23185529, 2012). "In contrast, Lcn2 promotes neutrophil recruitment during mycobacterial pulmonary infection, by inducing G-CSF and KC in alveolar macrophages." (PMID 23185529, 2012). "Importantly, we document a new role for Lcn2 in constraining and limiting lymphocytic inflammation and promoting neutrophilic accumulation during mycobacterial infections." (PMID 23185529, 2012). "The new role for Lcn2 presented in this paper is to constrain CXCL9 induction and lymphocytic accumulation during mycobacterial pulmonary infections." (PMID 23185529, 2012). "Thus far, it is not known whether Lcn2 plays a role in the inflammatory response to mycobacterial pulmonary infections." (PMID 23185529, 2012).
peripheral nerve injury (2 papers, 2023 to 2025). Injury to a peripheral nerve. "Following peripheral nerve injury, transient receptor potential vanilloid 4 (TRPV4) is upregulated, resulting in the release of lipocalin-2 (LCN2), which contributes to enhanced pain sensitivity." (PMID 41154475, 2025).
polycythemia vera (2 papers, 2020 to 2021). "In addition, LCN2 serum levels were significantly increased in polycythemia vera (PV) and MF and positively correlated with JAK2V617F and mutated CALR allele burden and neutrophil counts." (PMID 34439364, 2021).
prostate adenocarcinoma (2 papers, 2021 to 2022). "In summary, lipocalin-2 was highly expressed in about 36% of patients with prostate adenocarcinoma." (PMID 33542838, 2021).
relapsing-remitting MS (2 papers, 2023 to 2025). "To give more insight about the redox control of LCN2 induction in dysfunctional adipocytes, we aimed at using dimethylfumarate (DMF), a fumaric acid ester approved for the treatment of relapsing-remitting MS, which promote Nrf2-mediated antioxidant defense." (PMID 37517520, 2023).
retinal diseases (2 papers, 2020 to 2024). "LCN2 has been associated with several other retinal diseases, including AMD, but a role of LCN2 expression by the RPE, versus the retina and invading neutrophils, is not clear." (PMID 38528525, 2024).
salmonellosis (2 papers, 2014 to 2020). Infections with bacteria of the genus salmonella. "This study motivates the development of therapeutic interventions directed against this Lcn2-dependent, MMP-9-driven tissue degradation pathway to combat salmonellosis." (PMID 24465207, 2014).
schistosomiasis (2 papers, 2021). An infectious disease caused by parasitic trematodes of the genus Schistosoma that colonize human blood vessels and release eggs that can cause granulomatous reactions leading to acute (swimmer's itch or acute schistosomiasis syndrome) or chronic disease. "Here, we have found that LCN2 increased significantly in the early stage of schistosomiasis through preliminary biological information, then we explored the possible mechanism of increased LCN2 expression." (PMID 34616693, 2021).
serous adenocarcinoma (2 papers, 2009 to 2025). An adenocarcinoma that is characterized by the presence of papillary patterns and cellular budding.
spinal cord injury (2 papers, 2023). Penetrating and non-penetrating injuries to the spinal cord resulting from traumatic external forces (e.g., WOUNDS, GUNSHOT; WHIPLASH INJURIES; etc.). "Neutrophil gelatinase-associated lipoprotein (NGAL), a protein encoded by the lipocalcin-2 (LCN2) gene, has been reported to be involved in multiple processes of innate immunity, but its relationship with spinal cord injury (SCI) remains unclear." (PMID 36949855, 2023).
thyroid (2 papers, 2016 to 2021). "The mechanism by which LCN2 contributes to thyroid tumorigenesis is not known, but studies involving other neoplasms suggest that it might be related to the protein’s promotion of epithelial-mesenchymal transition and/or its ability to sequester iron." (PMID 27249794, 2016).
thyroid tumor (2 papers, 2018 to 2024). A benign or malignant neoplasm affecting the thyroid gland. "We conclude that the underexpression of CRABP1 and the overexpression of LCN2 may be useful diagnostic biomarkers in thyroid tumours with questionable malignity, and the overexpression of LCN2 and C1QL1 may be useful for prognostic purposes." (PMID 29321030, 2018).
acute lung injury (1 paper, 2023). A condition of lung damage that is characterized by bilateral pulmonary infiltrates (pulmonary edema) rich in neutrophils, and in the absence of clinical heart failure. "To confirm Lcn2 as a marker of pulmonary inflammation, we then examined Lcn2 levels upon LPS-induced acute lung injury (ALI)." (PMID 37746070, 2023).
acute-on-chronic liver failure (1 paper, 2020). Acute-on-chronic liver failure (ACLF) is an extreme condition during the natural history of chronic HBV infection, with a relatively high short-term mortality. "Recent studies showing that liver-derived LCN2 is a prognostic factor in a series of patients with acute-on-chronic liver failure, half of them being AH patients." (PMID 32968110, 2020).
bone metastasis (1 paper, 2023). Transfer of a neoplasm from its primary site to bones. "NCC patient plasma analysis has some limitations: (a) the cohort size in the analysis was small, (b) some of the osteolytic group patients had both osteolytic and osteoblastic bone metastasis, and (c) α1ACT and LCN2 are known as biomarkers of other diseases." (PMID 37408474, 2023).
Bovine mastitis (1 paper, 2020). INFLAMMATION of the UDDER in cows. "LCN2 rapidly increases during bacterial infections and inflammatory conditions, acts as a natural bacteriostatic agent through the interference with siderophore-mediated iron acquisition, and has been recommended as a potential marker of infection for bovine mastitis." (PMID 33195534, 2020).
brain edema (1 paper, 2017). Increased intracellular or extracellular fluid in brain tissue. "MMP-9 and LCN-2 released from activated neutrophils might contribute to the leakage of the blood-brain barrier and subsequent brain edema." (PMID 28409125, 2017).
celiac disease (1 paper, 2021). An autoimmune genetic disorder with an unknown pattern of inheritance that primarily affects the digestive tract. "Although there was some LCN2 stain detected also in celiac disease, DUOX2 staining was specific to the EED cases, and no LCN2 and DUOX2 was detected in controls." (PMID 33524399, 2021).
cerebral artery occlusion (1 paper, 2015). "Increased levels of LCN2 were observed in mouse serum as early as 1 hr after transient middle cerebral artery occlusion (tMCAO), reaching peak levels at 23 hrs." (PMID 25702801, 2015).
cervical tumors (1 paper, 2016). "LCN2 is highly expressed in cervical tumors (SCC, AD and ADSCC) compared with adjacent normal tissues." (PMID 26840566, 2016).
cholesteatoma (1 paper, 2012). A pathologic process characterized by the proliferation of keratinizing squamous epithelium resulting in the accumulation of keratin and cells in the middle ear and/or mastoid. "Real-time PCR of PI3, SPRR1B, LCN2 (lipocalin 2), MMP1, MMP9, MMP10, MMP12, SPP1, GJB2, Bcl-xl (BCL2L1), cIAP2 (BIRC3), S100A7A (koebnerisin), S100A9, SERPINB3, CEACAM6, KRT6B and SERPINB4 revealed that the expression levels of these proteins were higher in cholesteatoma than in external canal skin." (PMID 23285167, 2012).
chronic bronchitis (1 paper, 2022). A type of chronic obstructive pulmonary disease characterized by chronic inflammation in the bronchial tree that results in edema, mucus production, obstruction, and reduced airflow to and from the lung alveoli. "Adipsin, lipocalin-2, IL-6 and resistin were significantly higher in the group with chronic bronchitis." (PMID 36291711, 2022).
colonic adenomas (1 paper, 2007). "Additionally, LCN2 acts as a subunit of the MMP-9 that has been observed in increased levels in tumor cells in the transition from colonic adenomas to carcinomas." (PMID 17201907, 2007).
colonic polyps (1 paper, 2024). "Validation by qRT-PCR confirmed increased expression of the LCN2, IL1B, CXCL1, and CXCL3 genes in CCS colonic polyps." (PMID 38297356, 2024).
condyloma acuminatum (1 paper, 2016). "In the present study, we further supported these findings by not only providing quantitative data but also showing more LCN2 expression in verrucous epidermal nevus and condyloma acuminatum, which both harbor dysregulation of keratinocyte differentiation (parakeratosis) as other disorders above." (PMID 27551519, 2016).
Constipation (1 paper, 2015). Infrequent or difficult evacuation of feces. "Of the ten up-regulated genes, the largest decrease in the transcripts of constipation rats was observed for Serpina3n (0.19-fold), followed Lcn2, Slc5a8, C3, Rerg, and Arhgap8." (PMID 26151867, 2015).
cryptococcosis (1 paper, 2025). An acute or chronic, localized or disseminated infection by Cryptococcus neoformans. "Since IL-1β levels and the expression of its receptor (Il1rn) are high in H99-infected brains, it is probable that reduction in Lcn2 antagonizes the effects of this pro-inflammatory cytokine and serves as a protective mechanism to mitigate brain tissue damage during cryptococcosis." (PMID 40038673, 2025).
cystic kidneys (1 paper, 2025). "Notably, levels of Lcn2 transcripts significantly increased in Hoxb7-Cre; Pkd1f/f cystic kidneys compared to Hoxb7-Cre; Pkd1f/f; Ankmy2f/f P3 kidneys." (PMID 41474822, 2025).
Dent disease type 1 (1 paper, 2024). Dent disease type 1 is a type of Dent disease with predominantly renal manifestations. "In different Dent disease type 1 models, NGAL/Lipocalin 2 was shown to be overexpressed and even excreted." (PMID 39336766, 2024).
diarrhoea (1 paper, 2024). "Then, we selected only those participants that showed clinical diarrhoea, but the association between LCN2 levels and alpha diversity was still non-significant (p-value>0.05)." (PMID 38736752, 2024). "We examined the gut microbiota of travellers returning from tropical areas with and without traveller’s diarrhoea (TD) and its association with faecal lipocalin-2 (LCN2) levels." (PMID 38736752, 2024).
differentiated thyroid carcinoma (1 paper, 2018). Differentiated thyroid carcinoma (DTC), also known as papillary or follicular thyroid carcinoma, is a slow-growing malignancy usually presenting in adults as an asymptomatic thyroid mass. "Gene expression of C1QL1 (a), LCN2 (b), CRABP1 (c) and CILP (d) genes was measured by real-time quantitative PCR in normal thyroid (NT) tissues, follicular thyroid adenoma (FTA) and differentiated thyroid cancer (DTC)." (PMID 29321030, 2018).
enteritis (1 paper, 2025). Inflammation of the small intestine. "The experimental data revealed good discrimination for DUOX2, LCN2, and DEFA6 in normal individuals, enteritis patients, and IBD patients." (PMID 40830794, 2025).
Enterobacteriaceae Infections (1 paper, 2024). Infections with bacteria of the family ENTEROBACTERIACEAE. "Moreover, IL-22, derived from ILC3s, is crucial in regulating LCN2 production in human IECs, thereby facilitating host defense against Enterobacteriaceae infections." (PMID 39300068, 2024).
follicular thyroid adenoma (1 paper, 2018). A benign, encapsulated tumor, arising from the follicular cells of the thyroid gland. "LCN2 and CRABP1 were also differentially expressed in DTC when compared with follicular thyroid adenoma." (PMID 29321030, 2018).
gastric diseases (1 paper, 2025). "However, LCN2 as an effector of Lut has not been reported in gastric diseases." (PMID 40520011, 2025).
Gliosis (1 paper, 2025). Gliosis is the focal proliferation of glial cells in the central nervous system. "In gliosis, C3 and LCN2 genes, identified as reactive markers due to their complement activation, doubled in expression compared to senescence." (PMID 40719049, 2025).
hearing loss (1 paper, 2018). "S100A8 is the endogenous ligand for Toll like receptor 4 (TLR4) which activates NF-ĸB, whereas LCN2 is an NF-ĸB target gene and pro-inflammatory cytokine, that can itself activate the NF-ĸB pathway and is implicated in inflammation, neurodegeneration and noise-induced hearing loss." (PMID 30106954, 2018).
hematoma (1 paper, 2022). A hematoma is a collection of blood from a vascular structure into an extravascular space. "Nonetheless, LCN2 knockdown did not affect re-bleeding or hematoma absorption because the hemorrhagic severity of endovascular perforation-induced SAH was not significantly altered, as evidenced by the bleeding volume score and MRI." (PMID 35817941, 2022).
hemorrhagic disease (1 paper, 2018). Spontaneous or near spontaneous bleeding caused by a defect in clotting mechanisms (blood coagulation disorders) or another abnormality causing a structural flaw in the blood vessels (hemostatic disorders). "The first was Lcn2; because the protein is excreted in the urine, it may have diagnostic value for assessment of the prognosis of hemorrhagic diseases, similar to its use in human liver and renal disease." (PMID 29724035, 2018).
hidradenitis suppurativa (1 paper, 2020). A chronic suppurative and cicatricial disease of the apocrine glands occurring chiefly in the axillae in women and in the groin and anal regions in men. "In contrast, serum level of LCN2 was found to be elevated in hidradenitis suppurativa (HS) patients and LCN2 was also found to be up-regulated in lesional skin of HS patients." (PMID 33260746, 2020).
Hirsutism (1 paper, 2024). Abnormally increased hair growth referring to a male pattern of body hair (androgenic hair). "Furthermore, only the concentration of lipocalin-2 was positively correlated with the presence of hirsutism, which may also confirm the involvement of lipocalin-2 in hormonal disorders present in the course of PCOS." (PMID 39201400, 2024).